ADAM30 (ADAM metallopeptidase domain 30)
Description:
Plays a role in lysosomal amyloid precursor protein (APP) processing by cleaving and activating CTSD/cathepsin D which leads to APP degradation.
Synonyms: svph4
Tractability: Antibody: its Gene Ontology location is reachable by antibodies, with high confidence; UniProt predicts a signal peptide or a membrane-spanning region.
Gene: Protein-coding gene on chromosome 1 (119,893,533 to 119,896,515, reverse strand). Ensembl gene ENSG00000134249.
Subcellular location: Late endosome membrane
Subcellular location (Human Protein Atlas): Mid piece
Pathways (Reactome):
Reproduction: Interaction With Cumulus Cells And The Zona Pellucida
Gene Ontology:
Molecular function: metalloendopeptidase activity; metallopeptidase activity; zinc ion binding
Biological process: male gonad development; proteolysis
Cellular component: external side of plasma membrane; membrane; plasma membrane; sperm head plasma membrane; late endosome membrane
Genetic constraint (gnomAD): Loss-of-function variants: 1 observed, 0.87 expected, observed/expected ratio (o/e) 1.14, 90% interval 0.28 to 1.9. That is too few expected variants to judge how well the gene tolerates losing a copy. Missense variants: 960 observed, 1,013.3 expected, observed/expected ratio (o/e) 0.95, 90% interval 0.9 to 1. Synonymous variants: 382 observed, 362.41 expected, observed/expected ratio (o/e) 1.05, 90% interval 0.97 to 1.15.
Homologues: Orthologues: chimpanzee ADAM30 (99% identical), macaque ADAM30 (92% identical), rabbit ADAM30 (65% identical), pig ADAM30 (61% identical), rat Adam30 (53% identical), mouse Adam30 (53% identical), tropical clawed frog XB990656 (30% identical), zebrafish adam9b (29% identical), Caenorhabditis elegans unc-71 (24% identical), Drosophila melanogaster mmd (18% identical), zebrafish adam10a (17% identical), Drosophila melanogaster kuz (16% identical), and 2 more. Paralogues in human: ADAM21 (36% identical), ADAM20 (34% identical), ADAM9 (34% identical), ADAM29 (32% identical), ADAM2 (28% identical), ADAM12 (27% identical), ADAM19 (27% identical), ADAM32 (26% identical), ADAM33 (26% identical), ADAM22 (25% identical), ADAM11 (25% identical), ADAM23 (24% identical), and 8 more.
Diseases named in the same sentence as ADAM30 in open-access papers:
ADAM30 is named in the same sentence as 7 diseases in open-access papers, as found by Europe PMC text mining. Sharing a sentence is not in itself a finding about the gene and the disease. The quoted sentences say what the papers report.
type 2 diabetes (2 papers, 2009 to 2013). "We identified fourteen type 2 diabetes-associated genes discovered by the first waves of GWAS for which there was little prior evidence of their potential role in diabetes (Adam30, Adamts9, Camk1d, Cdc123, Cdkal1, Cdkn2a, Cdkn2b, Ext2, Hhex, Ide, Jazf1, Lgr5, Thada and Tspan8)." (PMID 23442068, 2013).
Alzheimer disease (1 paper, 2018). A progressive, neurodegenerative disease characterized by loss of function and death of nerve cells in several areas of the brain leading to loss of cognitive function such as memory and language. "Voxel-based analysis was then applied in a 3D histology study investigating the impact of the over-expression of the ADAM30 gene on Aβ plaque deposition in a transgenic mouse model of Alzheimer's disease." (PMID 30498427, 2018). "Then, it was applied to characterize the effect of ADAM30, a gene involved in the metabolism of the amyloid precursor protein, in a mouse model of Alzheimer's disease." (PMID 30498427, 2018).
Crohn disease (1 paper, 2015). A gastrointestinal disorder characterized by chronic inflammation involving all layers of the intestinal wall, noncaseating granulomas affecting the intestinal wall and regional lymph nodes, and transmural fibrosis. "ADAM15 is a metalloprotease, a member of the ADAM (a disintegrin and metalloproteinase) protein family that includes ADAM30, an existing candidate gene for Crohn's disease." (PMID 25743184, 2015).
ADAM30 also shares sentences with these, for which no sentence is quoted: astrocytic tumor (1 paper); brain tumor (1); diabetes (1); Obesity (1).